OPRM1 (opioid receptor mu 1)
Diseases named in the same sentence as OPRM1 in open-access papers (continued):
Sharing a sentence is not in itself a finding about the gene and the disease.
depression (continued). "Our findings revealed significant differential expression of genes such as Oprm1, BDNF, Tph2, and Zfp769 in the depression mouse model (p < 0.05)." (PMID 40656047, 2025). "This study predicted that linalool, p-cymene, α-terpinene, terpinen-4-ol, and α-terpineol primarily contribute to CBEO’s anti-depressant effect, mainly via interactions with OPRM1, PTGS2, ESR1, SLC6A4, DRD2, and NR3C1, the six depression-related targets." (PMID 38567354, 2024). "Lastly, six weeks after repetitive chemogenetic activation of the STT pathway, the mice showed heightened anxiety state but not depression-like behavior, similar to the activation of OPRM1+ RVMSC neurons." (PMID 41282163, 2025). "Genes including Oprm1 and BDNF demonstrated functional relevance in modulating neural activity and behavior, offering promising candidates for early diagnosis and individualized treatment of depression." (PMID 40656047, 2025). "The significant associations obtained for OPRM1 rs1799971, CLOCK rs1801260 and depression in the bivariate analyses did not remain in the multivariable analyses." (PMID 34330229, 2021). "We found that repetitive chemogenetic activation of OPRM1+ RVMSC neurons in healthy mice was sufficient to induce anxiety-like, but not depression-like, behaviors." (PMID 41282163, 2025). "OPRM1 genotype groups did not significantly differ in age, gender, IQ as measured by the vocabulary subscale of the Wechsler Abbreviated Scale of Intelligence (WASI), depressive symptoms as measured by the Beck Depression Inventory (BDI), or drug use." (PMID 21912675, 2011).
Anxiety (37 papers, 2004 to 2026). Intense feelings of nervousness, tension, or panic often arise in response to interpersonal stresses. "Significant associations were found between the BDNF rs6265 polymorphism and pain catastrophising, OPRM1 rs1799971 and anxiety, and MAOA rs1137070 and depressive symptoms." (PMID 41460692, 2026). "Similarity, the OPRM1 rs1799971 gene showed a significant association with anxiety levels (p < 0.05), as measured by the STAI‐S." (PMID 41460692, 2026). "The diagram lists genes associated with anxiety and addiction displaying a link through the OPRM1 gene." (PMID 40560842, 2025). "Anxiety (p-value 0.000), MoCA total score (p-value 0.000), and OPRM1(rs1799971)A/G polymorphism (p = 0.039)explained approximately 49% of the variability in the mental health dimension." (PMID 36042993, 2022). "We must however highlight the effect of the OPRM1 variant rs1799971, which was consistently associated, in both constructs, with Anxiety (Rho > 0.099, p‐value < 0.028)." (PMID 30656852, 2019). "In the present study, findings revealed a significant association between the OPRM1 rs1799971 and elevated anxiety levels, suggesting that this polymorphism may modulate affective responses in FM." (PMID 41460692, 2026). "From the neuroendocrine system‐associated genes, we might highlight the association among females between OPRM1 polymorphism and increasing levels of anxiety and somatization, concomitantly with lower Social Dysfunction scores." (PMID 30656852, 2019). "Specific variants were associated with key psychological traits: BDNF rs6265 with pain catastrophising, OPRM1 rs1799971 with anxiety, and MAOA rs1137070 with depressive symptoms." (PMID 41460692, 2026). "Taken together, these results indicate that intranasal OT had little effect on stereotyped behaviour in Oprm1 null mice but normalised their anxiety levels in the novelty-suppressed feeding test and induced analgesia in the tail immersion test." (PMID 39020142, 2024). "Together, these results indicate that repeated OT administration was not able to reduce stereotyped and perseverative behaviours or anxiety levels in Oprm1-/- mice." (PMID 39020142, 2024). "Reductions in the expression of Crh or its receptor, Crhr1, attenuated anxiety-like behavior, whereas reductions in the expression of Oprm1 improved social behavior." (PMID 25756305, 2015). "Consistent with anxiolytic properties, acute OT normalised anxiety levels in Oprm1 mutants." (PMID 39020142, 2024). "We observe significant enrichment of NTSR2, GPR88 and Gabrg1 in chloroquine-activated neurons, and relatively lower expression of OPRM1, PENK and Chrm1, suggesting that these genes could be critical candidates in regulating pruritis and its associated anxiety." (PMID 34032210, 2021). "There was a statistically significant interaction between OPRM1 and 5-HTT (df = 2, F = 3.19, P = 0.043), and a significant effect for the covariate anxiety (HAD-A) (df = 1, F = 4.45, P = 0.036)." (PMID 28282362, 2017).
alcohol dependence (35 papers, 2008 to 2025). Physical and psychological dependence on alcohol. "In addiction and substance use disorders, hypermethylation of the mu-opioid receptor (OPRM1) is linked to heroin and alcohol dependence, and these epigenetic changes can persist to influence relapse risk." (PMID 41234420, 2025). "Among the genes related to opioid receptors, OPRM1, which encodes the μ-opioid receptor, has been extensively investigated in the context of drug and alcohol dependence." (PMID 38474311, 2024). "The rs1799971 variant of OPRM1 has been the most frequently studied SNP for its association with alcohol dependence, though results have been inconsistent." (PMID 31004399, 2020). "MOR-encoding gene OPRM1 polymorphisms are found to be associated with alcoholism treatment and risk." (PMID 32440365, 2019). "Overall, statistically significant associations of OPRM1-A118G polymorphism with alcohol-dependence was detected only in the dominant model (OR 1.261, 95% CI 1.008, 1.578; p = 0.042)." (PMID 29070014, 2017). "We combed PubMed, Embase, Web of knowledge and CNKI databases in search of associations of alcohol dependence with the OPRM1 A118G polymorphism to cover the most information sourced from both Chinese and English studies." (PMID 29070014, 2017). "Studies have sought associations of the opioid receptor mu 1 (OPRM1) A118G polymorphism (rs1799971) with alcohol-dependence, but findings are inconsistent." (PMID 29070014, 2017). "In view of the significances of μ-opioid receptor systems in physiologic mechanisms of reward centers, it is safe to say that OPRM1-polymorphisms had an influence on alcohol-dependence risks." (PMID 29070014, 2017). "Certain variants in the OPRM1 gene may affect how individuals respond to rewards and stimuli, which, in turn, can impact their chances of developing alcohol dependency." (PMID 38474311, 2024). "Two allelic variants of the OPRM1 gene have also been modelled by humanisation of the first coding exon of mouse Oprm1, including one of two variants: the major 118A allele and the minor 118G allele linked to alcoholism." (PMID 31015419, 2019). "The link between Oprm1 polymorphism and alcohol dependence may be explained by different physiological responses to alcohol by persons with the various genotypes." (PMID 32440365, 2019). "Interestingly, high levels of craving, a positive family history of alcoholism and the presence of a specific functional polymorphism (Asn40Asp) of the mu-opioid receptor gene (OPRM1), are well known predictors of response to this drug." (PMID 26784248, 2016). "Similarly endogenous opioids are involved in hedonic responses to food and to drugs, and the functional A118G polymorphism in the OPRM1 has been associated with vulnerability for binge eating disorders and for alcoholism." (PMID 25077169, 2014). "In order to clarify the role of OPRM1 polymorphism in alcohol use disorders, we investigated the possible association of OPRM1 A118G polymorphism on alcohol consumption and on susceptibility to alcohol dependence in three large population-based study populations." (PMID 23729673, 2013). "However, within the context of substance addictions (namely alcohol dependence), the response to naltrexone is known to vary as a function of genetics (the OPRM1 polymorphism) and family history of alcoholism." (PMID 24109443, 2013). "Nevertheless, the therapeutic utility of naltrexone in alcohol dependence is limited, perhaps as a result of clinical and genetic heterogeneity: e.g. effects of naltrexone are stronger in the subgroup of alcoholic patients carrying the Asp variant of the mu-opioid receptor (OPRM1) A1118G SNP." (PMID 26141191, 2015). "Thus, it may be that polymorphisms in OPRM1 encode for a variant that influences a more narrowly defined risk factor for alcoholism." (PMID 18433502, 2008).
alcohol dependence (continued). "The increased methylation of the OPRM1 promoter is not only limited to OUD but has also been detected among individuals with alcohol dependence, suggesting that the hypermethylation is generally associated with substance use disorder and addiction." (PMID 32493461, 2020). "The association between OPRM1 polymorphism and alcohol use disorders was investigated in a study population comprising of 503 individuals with the DSM-IV diagnosis of alcohol dependence or alcohol abuse and their 506 age- and sex-matched controls." (PMID 23729673, 2013). "The candidate gene OPRM1 has previously been related to opioid treatment response, mainly in analgesia and alcohol dependence." (PMID 21589866, 2011). "Moreover, in those who suffer from alcohol dependance (125 cases/69 controls, both sexes), a high methylation of three CpGs in the promoter of OPRM1 (that codifies for the μ-opioid receptor protein) was found." (PMID 41153345, 2025). "For subgroup analyses of Caucasian or Asian group each considered separately, the OPRM1 A118G polymorphism did not have association with alcohol dependence in all five genetic models." (PMID 29070014, 2017). "Though lots of researches have sought associations of the OPRM1 A118G- polymorphism with alcohol-dependence, there was no consensuses." (PMID 29070014, 2017). "To conclude, our fairly large cohort-based material (503 individuals with diagnosis of alcohol dependence or abuse and their 506 age- and sex-matched controls) does not support any association between the OPRM1 A118G polymorphism and alcohol dependence." (PMID 23729673, 2013). "Therefore, genetic variations of OPRM1 might have an effect upon the risks of alcohol-dependence." (PMID 29070014, 2017). "However, it is important to point out that the OPRM1 gene is not the only determining factor in alcohol dependence." (PMID 38474311, 2024).
opioid dependence (32 papers, 2010 to 2025). "To identify the impact of genetic risk on the development of opioid dependence, we profiled mice homozygous for the protective A or risk G-allele of the Oprm1 gene." (PMID 40894067, 2025). "Studies among Caucasian populations have rarely shown an association between opioid dependence and the A118G polymorphic variant of the OPRM1 gene." (PMID 39595582, 2024). "In non-pregnant adults, increased DNA methylation in the promoter region of OPRM1 was associated with decreased expression of the gene, increased rates of opioid dependence, and higher doses of postoperative pain medications." (PMID 33763662, 2020). "Close associations are suspected of the OPRM1 A118G polymorphism (A > G) with nicotine, alcohol, and opioid dependence." (PMID 29070014, 2017). "In the recent years, big data has established very close associations between OPRM1-A118G polymorphism and nicotine, alcohol, and opioid-dependence." (PMID 29137427, 2017). "By mapping gene expression changes within the anatomical context of the mouse brain following opioid dependence, our integrative spatial transcriptomic analysis uncovers a fundamentally new understanding of how the Oprm1 A118G variant shapes the brain’s molecular response to chronic opioids." (PMID 40894067, 2025). "RELA protein plays a significant role in the downstream activation of the OPRD1 (also known as DOR, δ-opioid receptor, or delta-opioid receptor) is a paralog of OPRM1 associated with opioid dependence gene that encodes the delta-opioid receptor (DOR) protein in humans." (PMID 37434949, 2023). "The A118G polymorphism of the OPRM1 gene may influence the development of opioid dependence." (PMID 39595582, 2024). "Collectively, our findings suggest that genetic risk for opioid dependence at the Oprm1 locus may be reflected more strongly in glial cell adaptations rather than neuronal dysfunction, emphasizing the importance of oligodendrocyte-mediated neuroimmune interactions in opioid dependence." (PMID 40894067, 2025). "To determine how the Oprm1 A112G SNP influences brain network dynamics during opioid dependence, we used a network control theory approach." (PMID 38124015, 2024). "Using a mouse model of the Oprm1 SNP, our work revealed opioid-induced differences in network connectivity between sexes and opioid dependence states in AA and GG Oprm1 mice." (PMID 38124015, 2024). "Candidate genes OPRM1, rs1799971, rs7997012, and rs540825 in the MOR system are associated with opioid dependence." (PMID 31480739, 2019). "Altered DNA methylation levels in a number of genes (e.g., OPRM1) have been found in patients with alcohol or opioid dependence." (PMID 22591552, 2012). "One of the most extensively studied candidates is the mu opioid receptor gene (OPRM1) and its functional single nucleotide polymorphism (SNP) rs1799971 (A118G), which has been reported to affect the individual vulnerability to opioid dependence, although not in all studies." (PMID 24086514, 2013). "qPCR data revealed an increase of Oprm1 in PVT and a decrease in NAc, consistent with the key functional roles of these two regions in opioid dependence." (PMID 38376052, 2024).
Obesity (29 papers, 2012 to 2025). Accumulation of substantial excess body fat. "In humans, obesity is associated with decreased Oprm1 availability in the brain, which would support the notion that obesity raises fear levels." (PMID 30210279, 2018). "Finally, it was shown that the obesity associated to the Binge Eating Disorder (BED) is related to the A118G polymorphism of the mu-opioid receptor (OPRM1) gene." (PMID 23847466, 2013). "Expressions of this receptor have been negatively related to obesity and food cravings OPRM1 cerebral availability has been inversely related to external eating behaviors." (PMID 40376058, 2025). "Multiple studies have found that OPRM1 availability is negatively related to obesity and food addiction." (PMID 37893019, 2023). "Though there are fewer studies relating the OPRM1 gene to obesity, Positron Emission Tomography (PET) studies using the receptor agonist radiotracer 11C-carfentanil have specified the role of this receptor in obesity and eating behaviors." (PMID 37893019, 2023). "Methylation of the combined five CpG sites analyzed in the promoter region of OPRM1 showed a significant increase in DNA methylation of humans with obesity for a long time (>5 years from onset) (CTRLs = 7.36 ± 0.51, obese = 11.51 ± 0.95; p < 0.001)." (PMID 31258545, 2019). "We sought to extend the analysis of DNA methylation at CNR1 and OPRM1 promoters in the preclinical animal model to a group of humans with obesity and matched healthy controls (CTRLs)." (PMID 31258545, 2019). "We also observed the DNA methylation levels on CNR1 and OPRM1 gene promoters in humans with obesity and Ctrl stratified for gender." (PMID 31258545, 2019). "Additionally, when compared to controls, 13 women with obesity showed significantly decreased availability of OPRM1 in the ventral striatum, insula, and thalamus detected with [11(C)]carfentanil PET scans." (PMID 40376058, 2025). "Thus, here we clearly show the relevant role of CNR1 and OPRM1 transcriptional regulation as a possible biomarker for obesity and, due to the reversible nature of the epigenetic hallmark, our data open new avenue for environmental strategies of intervention." (PMID 31258545, 2019). "These alterations in genes regulation could contribute to the development of the obese phenotype, and we thus suggest CNR1 and OPRM1 epigenetic modulation as possible biomarkers of obesity development." (PMID 31258545, 2019). "Interestingly, maternal obesity during the periconception or gestational period increased expression of Oprm1 in the NAc of male offspring when measured at 14 weeks of age, whereas, maternal periconceptional obesity decreased expression of Oprm1 in the NAc of female siblings." (PMID 34312305, 2021). "We failed to observe any difference between controls and humans with obesity in the overall population, yet age-based stratification of the data clearly showed a significant reduction of the epigenetic hallmark at both CNR1 and OPRM1 promoters in younger (<30 years old) humans with obesity." (PMID 31258545, 2019). "The common targets of obesity, T2DM, and NAFLD are solute carrier family 6 member 4 (SLC6A4), acetylcholinesterase (ACHE), opioid receptor Mu 1 (OPRM1), and glycogen synthase kinase 3 beta (GSK3B)." (PMID 39575382, 2024). "DNA methylation changes at human CNR1 and OPRM1 gene promoters in controls (CTRL) and humans with obesity." (PMID 31258545, 2019). "With the aim to extend the study of CB1 and MOP receptors to human obesity, we assessed whether PBMCs might mirror central nervous system defects, and we then evaluated DNA methylation at CNR1 and OPRM1 gene promoters in PBMCs of humans with obesity." (PMID 31258545, 2019). "Moreover, to the best of our knowledge, OPRM1 expression in humans with obesity has not been studied yet, with the only available PET clinical study in different brain regions reporting lower MOP availability in obese subjects compared to controls." (PMID 31258545, 2019).